BCRP2 (BCR pseudogene 2)
Synonyms: BCR-2; formerly BCR2; BCRL2
Gene: Transcribed unprocessed pseudogene on chromosome 22 (21,115,929 to 21,119,758, forward strand). Ensembl gene ENSG00000169668.
Diseases named in the same sentence as BCRP2 in open-access papers:
BCRP2 is named in the same sentence as 1 disease in open-access papers, as found by Europe PMC text mining. Sharing a sentence is not in itself a finding about the gene and the disease. The quoted sentences say what the papers report.
breast carcinoma (1 paper, 2022). "To avoid confusion, we will be using henceforth BCRP2 as the human ABCG2, which was first isolated from multidrug resistant human breast cancer cells where it mediates resistance to the widely used drugs in breast cancer treatment anthracyclines." (PMID 36554670, 2022).